PLD3 (phospholipase D family member 3)
Diseases named in the same sentence as PLD3 in open-access papers (continued):
Sharing a sentence is not in itself a finding about the gene and the disease.
breast carcinoma (2 papers, 2014 to 2023). "This study aims to reveal the role and molecular mechanism of PLD3 and its embedded miR-6796 in breast cancer proliferation, thereby providing clues and a theoretical foundation for future research and development of therapeutic targets and prognostic markers." (PMID 37978168, 2023). "We proposed that PLD3 and miR-6796 can serve as prognostic factors and promising targets for breast cancer therapeutics." (PMID 37978168, 2023). "MTT and colony formation assays indicated that PLD3 depletion significantly promoted breast cancer cell proliferation." (PMID 37978168, 2023). "MDA-MB-231 was used to generate stable PLD3-overexpression cells (231-PLD3) and control cells (231-Vector) via lentiviral infection to explore the potential role of PLD3 in breast cancer progression." (PMID 37978168, 2023). "In our study, we revealed that miR-6796 functioned as a tumor suppressor gene in breast cancer proliferation when co-expressed with PLD3." (PMID 37978168, 2023). "For example, PLD3 is identified as one of irradiation-responsive genes in human lymphoblastoid cells, serving as a genetic modifier for breast cancer susceptibility genes BRCA1 and BRCA2, suggesting a role of PLD3 in DNA damage response." (PMID 25478031, 2014). "Its function is closely related to mitosis, implying that PLD3 may be involved in regulating the breast cancer cell cycle." (PMID 37978168, 2023). "In this study, we demonstrated that PLD3 and miR-6796 are co-expressed in breast cancer." (PMID 37978168, 2023). "This study may further explore the molecular mechanism of PLD3 inhibiting breast cancer cell proliferation." (PMID 37978168, 2023). "In the present study, we aim to investigate the role of PLD3 in breast cancer progression." (PMID 37978168, 2023). "Moreover, we confirmed that PLD3 was decreased in clinical breast cancer tissues and correlated with the poor prognosis of breast cancer patient." (PMID 37978168, 2023). "In conclusion, we revealed the role and molecular mechanism of PLD3 and its embedded miR-6796 in breast cancer proliferation, providing clues and a theoretical foundation for future research and development of therapeutic targets and prognostic markers for breast cancer." (PMID 37978168, 2023).
breast carcinoma (continued). "Furthermore, PLD3 overexpression could inhibit breast cancer cell proliferation, whereas lower PLD3 expression could promote breast cancer cell proliferation in vivo and in vitro." (PMID 37978168, 2023). "Afterward, we investigated whether PLD3 depletion could influence breast cancer progression." (PMID 37978168, 2023). "PLD3 overexpression inhibited CDK1 activity by binding to and phosphorylating it, resulting in mitotic arrest and consequently, inhibiting breast cancer proliferation." (PMID 37978168, 2023). "PLD3 can bind with CDK1 and inhibit its expression, leading to mitotic arrest and inhibiting breast cancer proliferation." (PMID 37978168, 2023). "PLD3, as the host gene of miR-6796, acts as a tumor suppressor gene in breast cancer, but the role of miR-6796 in breast cancer has not been reported." (PMID 37978168, 2023). "Further experimental verification demonstrated that PLD3 could bind to CDK, resulting in G2/M phase arrest, increased cell multinucleation, and promoted breast cancer cell apoptosis." (PMID 37978168, 2023).
cognitive decline (2 papers, 2019 to 2021). "In cognitive analyses, high prefrontal cortex expression of PLD3 was associated with a slower rate of global cognitive decline when adjusting for age at death, sex, postmortem interval, and the interval between the final neuropsychological assessment and death (β = 0.0002, p = 0.02)." (PMID 33830999, 2021). "When performing sensitivity analyses for cell type fraction leveraging the abundance of cell-specific single gene markers (e.g., ENO2 for neurons, GFAP for astrocytes, CD68 for microglia), PLD3 associations with β-amyloid and cognitive decline remained significant (p<0.05)." (PMID 33830999, 2021). "Increased PLD3 expression correlated with reduced rate of cognitive decline in the ROSMAP cohort and learning and memory in the AD-BXD mice." (PMID 33830999, 2021). "We also discovered that PLD3 expression levels correlate β-amyloid plaque density and the rate of cognitive decline in the longitudinal Religious Orders Study and Rush Memory and Aging Project." (PMID 33830999, 2021). "PLD3 mRNA levels in the human pre-frontal cortex inversely correlated with β-amyloid pathology severity and rate of cognitive decline in 531 participants enrolled in the Religious Orders Study and Rush Memory and Aging Project." (PMID 33830999, 2021).
Cognitive impairment (2 papers, 2021 to 2024). Abnormal cognition is characterized by deficits in thinking, reasoning, or remembering. "PLD3 mRNA levels in the human prefrontal cortex were shown to be inversely associated with the degree of amyloid pathology and the rate of cognitive impairment in 531 patients." (PMID 38528586, 2024). "Here, we leveraged multimodal datasets that reflect the role of PLD3 at a population level in both a large, longitudinal human study and in a genetically diverse murine model to establish a functional connection between PLD3 expression and AD-related cognitive impairment." (PMID 33830999, 2021).
colorectal cancer (2 papers, 2015 to 2016). A primary or metastatic malignant neoplasm that affects the colon or rectum. "Phospholipase D transforms lyso-PAF to choline and phosphatidic acid, and our data showed a clear reduction of PLD3 protein levels in hypoxia, a trend observed also for PLD3 mRNA vs hypoxia signature in colorectal cancer patients." (PMID 25605240, 2015).
frontotemporal dementia (2 papers, 2014 to 2025). Frontotemporal dementia (FTD) comprises a group of neurodegenerative disorders, characterized by progressive changes in behavior, executive dysfunction and language impairment, as a result of degeneration of the medial prefrontal and frontoinsular cortices. "By searching the genes coexpressed with PLD3 on COXPRESdb, we identified the human GRN gene encoding PGRN, whose mutation is responsible for frontotemporal lobar degeneration (FTLD) and neuronal ceroid lipofuscinosis, ranked as the second most significant gene coexpressed with PLD3." (PMID 25478031, 2014).
gastric cancer (2 papers, 2016 to 2021). A primary or metastatic malignant neoplasm involving the stomach. "Functional analysis of TRIM28, EIF4A2, NAP1L1, PLD3, RPL18A, and TRPM7 suggested that they play direct roles in gastric cancer." (PMID 27835598, 2016). "In addition, APBB1IP is a signature gene that contributes to clinical gastric cancer (GC) diagnosis and early detection, and the PLD4 and PLD3 enzymes strongly affect inflammatory cytokine production via the degradation of nucleic acids, thus serving as important regulators of inflammatory disease." (PMID 34916564, 2021).
Hepatitis (2 papers, 2019 to 2020). Inflammation of the liver. "PLD3 or PLD4-deficient mice displayed a TLR9-stimulated inflammatory syndrome while PLD3/4 double-deficient mice were unable to survive beyond the age of 21 days due to severe liver inflammation." (PMID 31354738, 2019). "Endolysosomal exonucleases, phospholipase D3 (PLD3), and PLD4 (type II transmembrane proteins) degrade TLR9, and their genetic deficiency causes an enhanced TLR9 expression and TLR9-dependent severe inflammation (lethal hepatitis), causing the death of newborns within two to three weeks after birth." (PMID 33643304, 2020).
melanoma (2 papers, 2019 to 2020). A malignant, usually aggressive tumor composed of atypical, neoplastic melanocytes. "Interestingly, some proteins that bind and process lipids, including phospholipase D3 (PLD3), inositol triphosphate protein kinase B (ITPKB), inositol triphosphate receptor 3 (ITPR3), fatty acid binding protein 3 (FABP3), have been found strongly upregulated in melanoma." (PMID 32528879, 2020).
osteosarcoma (2 papers, 2022). A usually aggressive malignant bone-forming mesenchymal neoplasm, predominantly affecting adolescents and young adults. "Pld3 represents an immune-related gene, with its low expression leading to a lower survival in patients with osteosarcoma." (PMID 36430209, 2022). "PLD3 has also been shown to be a prognostic protective gene for osteosarcoma, but this is the first time we have confirmed that it is also a B-cell marker gene for osteosarcoma." (PMID 36569871, 2022).
sarcoidosis (2 papers, 2021 to 2024). Sarcoidosis is a multisystemic disorder of unknown cause characterized by the formation of immune granulomas in involved organs. "SARS-CoV2 ORF8 host targets belonging to the sarcoidosis gene panel (IL17RA, EMC1, PLD3, GDF15, FKBP10, ADAM9, and PLAT) highlight significant pathways related to sarcoidosis pathogenesis." (PMID 34440765, 2021). "Sarcoidosis unique upregulated DEGs in response to LPS were FOXP1 (Forkhead Box P1), DDIT4 (DNA Damage Inducible Transcript 4), and IL7R, and unique downregulated DEGs in sarcoidosis were PYCARD (Caspase Recruitment Domain-Containing Protein 5), CD4, and PLD3 (Phospholipase D Family Member 3)." (PMID 39284999, 2024).
aging (1 paper, 2017). A developmental process that is a deterioration and loss of function over time. "On another note, there was an association of cognitive aging with 3 SNPs within the PLD3 gene, particularly the rs11672825 SNP." (PMID 28199971, 2017).
anemia (1 paper, 2021). A reduction in the number of red blood cells, the amount of hemoglobin, and/or the volume of packed red blood cells. "Unc93b13d/3dPld3−/−Pld4−/− mice had a substantially normalized phenotype compared to Pld3−/−Pld4−/− or Tlr9CpG11/CpG11Pld3−/−Pld4−/− mice, as they survived for >8 months and lacked splenomegaly, anemia and thrombocytopenia." (PMID 34620855, 2021).
autosomal dominant spinocerebellar ataxia (1 paper, 2018). "Most interestingly, another genetic variant in PLD3, p.Leu308Pro, was recently found to cause autosomal dominant spinocerebellar ataxia, a neurodegenerative condition where lysosomal disturbances are thought to be crucial." (PMID 30208929, 2018).
cerebellar degeneration (1 paper, 2021). Degeneration of the cerebellum. "We confirmed the reduction of Zfp212 and Pld3 in the Cb of an alcohol-induced cerebellar degeneration mouse model, suggesting that the ZNF212–PLD3 relationship is important for Purkinje cell survival." (PMID 34815492, 2021).
hemophagocytic lymphohistiocytosis (1 paper, 2021). "Moreover, Pld3−/−Pld4−/− mice accumulate small ssRNAs and develop spontaneous fatal hemophagocytic lymphohistiocytosis (HLH) characterized by inflammatory liver damage and overproduction of Interferon (IFN)-γ." (PMID 34620855, 2021).
Hemophagocytosis (1 paper, 2021). Phagocytosis by macrophages of erythrocytes, leukocytes, platelets, and their precursors in bone marrow and other tissues. "However, other histological abnormalities were still present, albeit less severe than in Pld3−/−Pld4−/− mice, including infiltrates of CD68+ myeloid cells, hepatomegaly, multifocal medullary hematopoiesis, and hemophagocytosis." (PMID 34620855, 2021).
Huntington disease (1 paper, 2022). Huntington disease (HD) is a rare neurodegenerative disorder of the central nervous system characterized by unwanted choreatic movements, behavioral and psychiatric disturbances and dementia. "The phospholipase D3 (PLD3), found in neuronal lysosomes, was found reduced in the striatum of Huntington’s disease mice." (PMID 36523271, 2022).
pancreatic ductal carcinoma (1 paper, 2022). "By analysing PanCancer genomic data, we then asked whether PLCD4, PLCB4 and PLD3 levels correlate to the pathogenesis of human pancreatic ductal carcinoma." (PMID 35255936, 2022).
Senile plaques (1 paper, 2014). Senile plaques are extracellular deposits of amyloid in the gray matter of the brain. "In contrast, PLD3-labeled senile plaques were barely found in non-AD brains (data not shown)." (PMID 25478031, 2014).
small cell lung carcinoma (1 paper, 2025). Small cell lung cancer (SCLC) is a highly aggressive malignant neoplasm, accounting for 10-15% of lung cancer cases, characterized byrapid growth, and early metastasis. "One study developed a risk prediction model utilizing a panel of five AAb biomarkers, including anti-PLD3 AAbs, for the early diagnosis of small-cell lung cancer." (PMID 40768895, 2025).
steatosis (1 paper, 2021). Increased lipid within the cytoplasm of cells. "This pathology was, however, distinguishable from the disease of Pld3−/−Pld4−/− mice as microvesicular steatosis was less prominent and the livers contained large numbers of erythrocytes." (PMID 34620855, 2021). "In contrast to Pld3−/−Pld4−/− liver tissue, analysis of Tlr9CpG11/CpG11Pld3−/−Pld4−/− liver histopathology revealed a lack of microvesicular steatosis." (PMID 34620855, 2021).
Thrombocytopenia (1 paper, 2021). A reduction in the number of circulating thrombocytes. "Comparison of Tlr9−/−Pld3−/−Pld4thss/thss mice to Tlr9+/–Pld3−/−Pld4thss/thss littermates and to Unc93b13d/3dPld3−/−Pld4−/− mice revealed that complete TLR9 deficiency significantly ameliorated some abnormalities caused by PLD3/4 deficiency, such as thrombocytopenia." (PMID 34620855, 2021).
tumor (8 papers, 2014 to 2026). "The combined increased abundances observed in the proteins encoded by Cav1, Pld3 and Hk3 also highlight the interplay with tumor cell metabolism modifications, leading to the suppression of cancer cell stemness and the deleterious effects of cancer-associated fibroblasts." (PMID 36430209, 2022). "By integrating molecular docking with tumor models, we assessed the therapeutic potential of targeting macrophage-specific PLD3 in tumor progression and immunotherapy resistance." (PMID 42163781, 2026). "Collectively, PLD3 promotes tumor progression and immunotherapy resistance by modulating lysosomal-AKT-NF-κB axis, thereby driving macrophage senescence and anti-inflammatory phenotype." (PMID 42163781, 2026). "In the deep tumor region, a similar correlation was observed for PLD3, alphaB-crystallin, CCN family member 2 or connective tissue growth factor (CTGF), and CD2-associated protein, while OGDH-E1 showed an opposite trend." (PMID 39195201, 2024). "Cytoplasmic aspartate aminotransferase (cAspAT), neural Wiskott–Aldrich syndrome protein (N-WASP), and 5′–3′ exonuclease phospholipase D3 (PLD3) were identified as less-abundant proteins in the deep part of the tumor." (PMID 39195201, 2024). "The 231-PLD3 and 231-Vector cells were injected into mice mammary fat pads to evaluate the effect of PLD3 expression on tumor growth in vivo." (PMID 37978168, 2023). "As hypothesized, we observed that orthotopic tumor volume was significantly lower in the PLD3-overexpression group than in the control group." (PMID 37978168, 2023). "Additionally, PLD3, which we found to be downregulated in both the cytoplasmic and membrane protein fraction of the F1 tumor samples compared to the patient material, has been shown to be a potential marker of senescence." (PMID 36983764, 2023). "Analyzing the whole-blood expression signature of four growth factor-related genes (ARAF, BRAF, KRAS, and RAF-1) and four genes involved in metabolism (ATP6V1H, OAZ2, PANK2, and PLD3), combined with tumor grade, they were able to predict the efficacy of PRRT with an accuracy of 95%." (PMID 33809226, 2021). "PLD3, which is involved in many signaling pathways, was indicated as a CRC hallmark for the first time in this study, and it underlines the negative correlation exhibited by PLD3 with the budding index in the deep part of the tumor where the protein was shown to be a less-abundant protein." (PMID 39195201, 2024).
cancer (6 papers, 2019 to 2025). A tumor composed of atypical neoplastic, often pleomorphic cells that invade other tissues. "PLD3, a member of the phosphodiesterase family, is believed to play a role in cancer development and progression." (PMID 40768895, 2025). "Further research is warranted to fully unravel the clinical significance of both anti-SNRPA and anti-PLD3 AAbs and their potential implications in different cancer patient populations." (PMID 40768895, 2025). "Overall, our knowledge of the role of PLD3/4 in cancer is limited, and thus additional research is warranted." (PMID 35883600, 2022). "Although PLD4 and PLD3 have been linked through murine models and genome-wide association studies to autoinflammatory diseases and late-onset Alzheimer’s disease, respectively, very little evidence exists regarding their involvement in cancer." (PMID 35883600, 2022). "PLD3 is related to insulin-mediated phosphorylation of the AKT pathway, suggesting that it may play a role in the occurrence and development of malignant tumors." (PMID 37978168, 2023).